GALNT17 (polypeptide N-acetylgalactosaminyltransferase 17)
Description:
May catalyze the initial reaction in O-linked oligosaccharide biosynthesis, the transfer of an N-acetyl-D-galactosamine residue to a serine or threonine residue on the protein receptor.
Synonyms: WBSCR17; GALNTL3; GalNAc-T5L; GalNAc-T19; GalNAc-T17; ppGalNAc-T17; GALNACT17; GALNT20
Tractability: Antibody: UniProt predicts a signal peptide or a membrane-spanning region.
Gene: Protein-coding gene on chromosome 7 (71,132,144 to 71,713,600, forward strand). Ensembl gene ENSG00000185274.
Subcellular location: Golgi apparatus membrane
Subcellular location (Human Protein Atlas): Golgi apparatus; Nucleoplasm; Nuclear bodies; Nucleoli
Pathways (Reactome):
Metabolism of proteins: O-linked glycosylation of mucins
Gene Ontology:
Molecular function: polypeptide N-acetylgalactosaminyltransferase activity
Biological process: protein O-linked glycosylation; protein O-linked glycosylation via N-acetyl-galactosamine
Cellular component: Golgi apparatus; Golgi membrane
Genetic constraint (gnomAD): Loss-of-function variants: 29 observed, 64.78 expected, observed/expected ratio (o/e) 0.45, 90% interval 0.33 to 0.61. The upper end of that interval is the gene's LOEUF score, 0.61, which puts it in group 2 of 6, group 1 being the genes least tolerant of losing a copy. Missense variants: 603 observed, 829.02 expected, observed/expected ratio (o/e) 0.73, 90% interval 0.68 to 0.78. Synonymous variants: 305 observed, 328.27 expected, observed/expected ratio (o/e) 0.93, 90% interval 0.85 to 1.02.
Homologues: Orthologues: macaque GALNT17 (100% identical), rabbit GALNT17 (99% identical), dog GALNT17 (99% identical), rat Galnt17 (99% identical), guinea pig GALNT17 (99% identical), mouse Galnt17 (98% identical), pig GALNT17 (98% identical), tropical clawed frog galnt17 (89% identical), chimpanzee GALNT17 (84% identical), zebrafish galnt17 (72% identical), Drosophila melanogaster Pgant5 (31% identical), Caenorhabditis elegans gly-3 (31% identical), and 11 more. Paralogues in human: GALNT9 (62% identical), GALNT18 (50% identical), GALNT8 (42% identical), GALNT10 (32% identical), GALNT13 (32% identical), GALNT1 (32% identical), GALNT5 (31% identical), GALNT4 (31% identical), GALNT6 (31% identical), GALNT11 (30% identical), GALNT7 (30% identical), GALNTL6 (30% identical), and 7 more.
Diseases named in the same sentence as GALNT17 in open-access papers:
GALNT17 is named in the same sentence as 19 diseases in open-access papers, as found by Europe PMC text mining. Sharing a sentence is not in itself a finding about the gene and the disease. The quoted sentences say what the papers report.
breast carcinoma (3 papers, 2015 to 2025). "Finally, in human, GALNT17 gene is differentially methylated in breast cancer and is included in seven gene signatures that allow us to distinguish between low- and high-risk breast cancers." (PMID 40943469, 2025). "Further studies are required to elucidate the role of GALNT17 methylation/expression in breast cancer." (PMID 40943469, 2025). "Two coding genes, AUTS2 and GALNT17, were located within a 500 MBp window around the 45 highly correlated variants, but the expression of neither of the two was associated with breast cancer survival in KMplotter analyses of TCGA data." (PMID 30787463, 2019).
AUTS2 syndrome (2 papers, 2019 to 2025). "These pathways, coupled with the translocation’s selective effects on Auts2 isoforms and coordinated dysregulation of Galnt17, suggest novel hypotheses regarding the etiology of the human “AUTS2 syndrome” and the wide array of neurodevelopmental disorders linked to variance in this genomic region." (PMID 31554716, 2019). "Several symptoms of AUTS2 syndrome and features of Galnt17 KO mice are strikingly similar to those of WBS patients." (PMID 40943469, 2025). "Although Galnt17 mutations have not been investigated, several phenotypes detected in 16GsoT/T mice overlap obviously with those of Auts2 KO mutants, and share features with human AUTS2 syndrome patients as well." (PMID 31554716, 2019). "On the other hand, observed behavioral and social phenotypes of the Galnt17 KO mice at least in part are similar to those seen in WBS and AUTS2 syndrome patients." (PMID 40943469, 2025).
developmental delay (2 papers, 2019 to 2025). "Mice with Galnt17 KO show symptoms of ASD, including developmental delay, anxiety, etc., while in dogs the TE-mediated downregulation of GALNT17 expression is associated with increased sociability towards humans." (PMID 40943469, 2025).
Parkinson disease (2 papers, 2022 to 2025). A progressive degenerative disorder of the central nervous system characterized by loss of dopamine producing neurons in the substantia nigra and the presence of Lewy bodies in the substantia nigra and locus coeruleus. "Several SNPs in GALN17 gene are linked to the development of Parkinson’s disease (PD), but no structural variants in GALNT17 have been definitely associated with the development of neurobehavioral disorders in human." (PMID 40943469, 2025).
cancer (2 papers, 2019 to 2022). A tumor composed of atypical neoplastic, often pleomorphic cells that invade other tissues. "Namely, increased B3GNT4 expression was associated with subclonal expansion in at least seven tumor types, while GALNT16 and GALNT17 levels appeared mostly associated with a decrease in intra-tumor heterogeneity across five cancers." (PMID 36009354, 2022).
GALNT17 also shares sentences with these, for which no sentence is quoted: autism (2 papers); glioma (2); Intellectual disability (2); neurodevelopmental disorder (2); Alzheimer disease (1); Anxiety (1); attention deficit-hyperactivity disorder (1); cognitive decline (1); colon cancer (1); mental illnesses (1); microcephaly (1); schizophrenia (1); tumor (1); Williams-Beuren syndrome (1).